RNU6-224P (RNA, U6 small nuclear 224, pseudogene)
Gene: Small nuclear RNA gene on chromosome 4 (131,273,242 to 131,273,348, forward strand). Ensembl gene ENSG00000206782.
Homologues: Orthologues: chimpanzee U6 (99% identical), macaque U6 (93% identical). Paralogues in human: RNU6-477P (92% identical), RNU6-15P (90% identical), RNU6-1013P (89% identical), RNU6-10P (89% identical), RNU6-1145P (89% identical), RNU6-188P (89% identical), RNU6-207P (89% identical), RNU6-21P (89% identical), RNU6-38P (89% identical), RNU6-639P (89% identical), RNU6-1 (88% identical), RNU6-1060P (88% identical), and 1286 more.